MDK (midkine)
Diseases named in the same sentence as MDK in open-access papers (continued):
Sharing a sentence is not in itself a finding about the gene and the disease.
cancer (continued). "MDK is a cytokine with complex functions in the nervous system, inflammation, cancer, tissue protection/repair and so on." (PMID 29872508, 2018). "Midkine has been reported to be strongly expressed in cancer cells and in inflammation and repair processes, and to be involved in the pathogenesis of various diseases." (PMID 28811360, 2017). "The high expression levels of midkine and pleiotrophin in many types of cancers make them excellent as biomarkers and therapeutic targets for cancer." (PMID 27903979, 2017). "The biological activities of midkine in malignant tumors include proliferation, angiogenesis, invasion and metastasis." (PMID 27974680, 2016). "MDK was first characterized in murine carcinoma cells, and it plays important roles in the release of growth factors during inflammation." (PMID 27040083, 2016). "Previous reports have also established that other promoters, such as the AFP, Rad51C, human telomerase reverse transcriptase (hTERT), and midkine promoters, are expressed in a majority of human cancers." (PMID 26498690, 2015). "ChIP experiments show that the Sp1 occupies its binding sites in the promoters of XIAP, CRABP1, MDK, and KCNMA1, and that DIG-MSK decreases Sp1 binding to them with a superior effect on KCNMA1, a gene associated with high proliferation in cancer cells." (PMID 25110883, 2014). "Several systems expressing toxic or suicide genes driven by other cancer specific promoters such as hTERT, Tyrosinase, Survivin and Midkine were developed in the past decade." (PMID 24742710, 2014). "The recognition of the potential role of the MDK pathway in the treatment of cancer has increased efforts to identify MDK inhibitors." (PMID 23976985, 2013). "In contrast to earlier reports in which MDK gene and protein expression was determined to be higher in late stage cancer, we observed a drop in the levels of MDK mRNA in CRPC versus RAD." (PMID 20868494, 2010). "More detailed analysis of two of the cancer related genes, sox-2 and midkine, confirmed that their expression levels increased following 5-Aza-2-deoxycytidine treatment." (PMID 20019818, 2009). "De novo expression of MDK in cancer cells not normally expressing MDK confers a multi-drug resistance, while knockdown of MDK in cancer cells that normally expressed the protein leads to chemosensitization." (PMID 18794772, 2008). "By immunohistochemical staining, we found that MDK expression was confined primarily to the cytoplasm of cancer cells and showed a diffuse staining pattern (Late Stage Cancer), which was consistent with the previous report." (PMID 18275606, 2008). "At the same time, midkine is involved in the development of cancer because of its mitogenic effect, promotion of angiogenesis, anti-apoptotic activity, fibrinolytic activity, and transforming activity." (PMID 18717994, 2008). "Midkine expression is increased in a number of malignant tumors, including esophageal, stomach, colon, hepatocellular, breast and pancreatic carcinoma, when compared with the level of expression in adjacent non-cancerous tissues." (PMID 18717994, 2008). "Midkine is a heparin-binding growth factor that is over-expressed in various human cancers and plays important roles in cell transformation, growth, survival, migration, and angiogenesis." (PMID 18275606, 2008). "Prostate tissue microarray slides containing 129 cases (18 normal prostate tissues, 40 early stage cancers, and 71 late stage cancers) were assessed for midkine expression by immunohistochemical staining." (PMID 18275606, 2008). "The results indicate regulation of midkine gene expression in cancer cells (MDK) appears to modulate sensitivities to anticancer drugs." (PMID 18794772, 2008). "Midkine expression in blood and cancer tissues is indicative of a strong relationship with malignant potential, and high MK expression suggests a bad prognosis." (PMID 18682710, 2008). "Midkine is overexpressed in many carcinomas and thought to play an important role in carcinogenesis." (PMID 17622248, 2007).
cancer (continued). "The level of expression of midkine (MK), a heparin-binding growth factor, is increased in many types of human carcinomas." (PMID 10952771, 2000). "It has been suggested that a heparin-binding growth factor, midkine (MK), plays an important role incarcinogenesis because of its frequent overexpression in various malignant tumours." (PMID 10408712, 1999). "Taken together, the results from these studies suggest that MDK may be involved in promoting drug resistance via enhancing persistence of the cancer stem cell population in cancers exposed to chemotherapies." (PMID 40429950, 2025). "Furthermore, as compared to healthy controls, patients with several cancers have been shown to exhibit upregulated s‐MDK expression, which is useful as a noninvasive parameter for assessing disease diagnosis and progression." (PMID 40620228, 2025). "Specifically, Ugonin P blocks cancer-induced osteoclast formation by reducing MDK production." (PMID 40520001, 2025). "Moreover, intercellular communication analysis revealed that the MDK signaling pathway plays an important role in the communication between cancer cells and macrophages in EGFRvIII-mutant GBM." (PMID 40527884, 2025). "In addition, increased MDK expression was observed in all drug-resistant cancer cell lines in a separate study, further supporting its involvement in MDR mechanisms across human malignancies." (PMID 40500394, 2025). "Several studies suggest that MDK gene expression may protect cancer cells against various chemotherapeutic agents, including doxorubicin, cannabinoids, and adriamycin." (PMID 40500394, 2025). "After MDK was discovered in 1988, it soon became a spotlight target in cancer research." (PMID 40835683, 2025). "MDK, a pro-tumorigenic growth factor, is highly expressed in various cancers." (PMID 40396179, 2025). "For example, a pilot study evaluating MDK levels in fine needle aspiration samples found elevated MDK in malignant tumors relative to benign ones in only a small subset of cases, and whether this subset carries prognostic value has not been explored." (PMID 40429950, 2025). "Midkine (MDK) is a heparin‐binding growth factor involved in various biological processes, including cell proliferation and chemotherapeutic resistance, in diverse cancers." (PMID 40620228, 2025). "MDK overexpression has been documented in a variety of cancers, including those that affect women." (PMID 40429950, 2025). "These regulatory pathways may enhance the ability of cancer cells to acquire resistance through MDK overexpression." (PMID 40500394, 2025). "However, in the context of cancer, MDK generally promotes immunosuppression by regulating the various cell populations of immune cells, including Tregs." (PMID 40429950, 2025). "Due to MDK’s diverse effects on cancer cells and the fact that MDK-deficient mice exhibit no major abnormalities, MDK makes an appealing target in women’s cancers." (PMID 40429950, 2025). "While MDK promotes cancer cell motility, its function in cancer-mediated bone metastasis remains a mystery, suggesting it could be a potential target for remedying osteolytic bone metastasis." (PMID 40520001, 2025). "However, of note, MDK interacts with a variety of plasma membrane receptors controlling also many cancer-related behaviors." (PMID 39300217, 2024). "While most literature focuses on MDK’s role in cancer progression and its potential as a therapeutic target due to its involvement in cell growth, survival, metastasis, migration, and angiogenesis in various cancers." (PMID 38694874, 2024). "Recently, researches on MDK had escalated, especially in the field of cancer." (PMID 39014225, 2024). "When MDK is genetically silenced, it leads to a decrease in the proliferation of cancer cells." (PMID 37240085, 2023). "In these lines, MDK-targeted strategies may have great therapeutic potential, particularly in refractory cancer settings." (PMID 38098484, 2023).
cancer (continued). "Upregulation of midkine can promote growth, survival, metastasis, and angiogenesis of cancer cells." (PMID 36906597, 2023). "In our study, midkine expression in pan-cancer was evaluated by TIMER database." (PMID 36906597, 2023). "Many studies have reported MDK’s role in cancer progression and drug resistance." (PMID 37240085, 2023). "However, further studies are needed to clarify MDK signaling pathways involved in CNS pathologies, but also cancer progression, metastasis, inflammation, and other peripheral pathological conditions." (PMID 38098484, 2023). "Besides its various functions in cancer, MDK has been described as an important regulator of autoimmune and inflammatory diseases." (PMID 38098484, 2023). "Thus, the promoter region of the midkine gene can be used to control gene expression required for adenovirus replication to restrict the expression of introduced genes to cancer cells only." (PMID 37367056, 2023). "Metformin may counteract MDK in almost every way that contributes to MDK’s ability to contribute to cancer growth; hence metformin may act as a possible MDK inhibitor." (PMID 37240085, 2023). "AS a heparin-binding growth factor, MDK is abnormally high expressed in a variety of human malignancies and serves as an intermediary agent for the acquiring critical features of cancer, such as proliferation, metastasis, chemoresistance, migration, and angiogenesis 35-38." (PMID 36594100, 2023). "The MDK and NAMPT ligand–receptor cellular crosstalk between the cancer associated fibroblasts and other cell clusters may mechanistically cause immune escape." (PMID 37065499, 2023). "One of these Ifs, IF-γ, is exploited to combat different types of cancer, but reports indicate that the same aids in metastasis; upon investigation was found that MDK is the response element of IF-γ and is responsible for IF-γ induced metastasis in different cancers." (PMID 37240085, 2023). "MDK is found to be a putative gene involved in the drug resistance of various cancers." (PMID 37240085, 2023). "HIF-1α induces MDK expression during hypoxic conditions, increasing the vascularization of the small pulmonary arteries and paving the vasculature, providing the basic regulatory elements needed for the cancer cells to survive." (PMID 37240085, 2023). "MDK is an emerging player in drug resistance in various cancers." (PMID 37240085, 2023). "We found that midkine was significantly upregulated in a variety of cancers, including HCC." (PMID 36906597, 2023). "Midkine was reported to promote cancer cell proliferation by repressing the LKB1-AMPK axis." (PMID 37047258, 2023). "This speculation was preliminarily supported by the significant correlations between STAT1 and MDK in various cancers in the TCGA database." (PMID 35747815, 2022). "All these demonstrate that IFN-γ activates MDK via STAT1 in cancer cells." (PMID 35747815, 2022). "To understand whether MDK affects AMPK-related signaling pathways in different cancers, we performed a gene expression correlation-based gene set enrichment analysis (GSEA)." (PMID 35487917, 2022). "MDK has been reported to promote cancer EMT via TGF-β, WNT and Notch 2 signalings." (PMID 35747815, 2022). "Other relevant effects of MDK in cancer are promotion of angiogenesis, upregulation of integrin mediated cell migration (osteoblast‐like cells) and, through Notch2 binding, induction of epithelial mesenchymal transition (EMT) (immortalized HaCaT keratinocytes)." (PMID 35445563, 2022). "This gave rise to the speculation that whether IFN-γ treatment in cancers would result in MDK activation, thereby triggering EMT and metastasis." (PMID 35747815, 2022). "Among these, we found interactions that may constitute potential targets for CAFs-based therapies, such as THBS2/THBS3 (myCAF2) and CD47 (cancer cells) or between MDK (CAFs) and SDC2/SDC4/NCL (cancer cells)." (PMID 36352420, 2022). "Expression of midkine (mRNA and protein expression) is increased in several cancers, including HCC." (PMID 36518320, 2022).
cancer (continued). "MDK was reported to be abnormally expressed in human malignancies and participate in diverse cancer development and progression processes 46, suggesting that MDK expressed on different cells may be a double-edged sword in the TME." (PMID 36438481, 2022). "This negative expression of MDK may be due to gene methylation in the MDK genomic region or transcriptional regulation in particular cancer cells instead of genome deletion." (PMID 35487917, 2022). "Taken together, these results suggest that MDK suppresses AMPK activation in human cancer cells." (PMID 35487917, 2022). "Midkine enhances the angiogenic and proliferative activities of cancer cells." (PMID 36518320, 2022). "The function of MDK in cancer cell invasion in vitro was then examined." (PMID 33456569, 2021). "Moreover, Midkine had differently expression at high levels in malignant tumors and acted as a critical substance to promote the growth and metastasis of cancers." (PMID 33748185, 2021). "It is tempting to speculate that the dual ability of BO‐110 to target both MDK in cancer cells, and VEGFR3 in lymphatic cells, may represent an advantage with respect to other antilymphangiogenic agents." (PMID 34762341, 2021). "In addition, expression of MDK in cancer stem cells was determined after miR‐188 mimic administration." (PMID 32592428, 2020). "Midkine (MDK) is an heparin‐binding growth factor that is upregulated in various human malignancies and plays an important role in promoting growth, survival, and migration of cancer cells, as well as cancer angiogenesis and metastasis." (PMID 32841536, 2020). "Midkine released from CAFs can block cisplatin-induced cancer cell death." (PMID 33050576, 2020). "Current studies have reported that MDK has a role in cancer disease in several organs." (PMID 31905498, 2020). "Midkine (MDK) is a heparin-binding growth factor that is overexpressed in various types of human cancers, but its clinical significance is still unknown in CCA." (PMID 33193605, 2020). "MDK has also been found to be important in the process of human carcinogenesis, which might be a potential target for cancer therapy." (PMID 32592428, 2020). "Therefore, Midkine silencing is proposed as a potential therapy for limiting cell cycle progression in cancer stem cells." (PMID 31882403, 2020). "Overexpression of MDK was introduced in cancer stem cells through lentiviral vectors." (PMID 32592428, 2020). "MDK-induced NF-κB also increased cancer cell proliferation through PI3K-Akt signaling and Hes1 triggered epithelial-to-mesenchymal transition via increased Vimentin and Snail levels, and decreased E-cadherin levels, which were not recovered by survivin expression under MDK knock down and hypoxia." (PMID 32847073, 2020). "Small-molecule midkine inhibitors have been investigated mainly in the field of cancer therapy." (PMID 31031625, 2019). "MDK expressed by malignancies may support lymphatic metastases by inducing neo-lymphangiogenesis, raising the possibility that plasma MDK may be useful for a biomarker in detection of invasive status of cancers." (PMID 31648221, 2019). "Interestingly, MDK was identified as one of the top candidates, which had been shown to enhance the angiogenic and proliferative activities of cancer cells." (PMID 30001734, 2018). "Midkine (MDK) is a heparin-binding growth factor prominently expressed in embryonic tissues but down-regulated to negligible levels in healthy tissues of adults, which is considered to be a “pan-cancer” biomarker." (PMID 30001734, 2018). "In addition, several cancer types are showed to have an up-regulated expression of Midkine, which results in the promotion of cell survival factors as well as obstruction of apoptosis through caspase-3 inhibition." (PMID 29843646, 2018).
cancer (continued). "It has been reported that midkine is overexpressed in at least 20 different types of cancers, ranging from the most common cancers to some of the rarest, and acts as a key factor associated with recurrent invasive and metastatic phenotypes of most malignant tumors." (PMID 28430645, 2017). "Midkine, a heparin-binding growth factor, has been identified as a promising cancer biomarker." (PMID 27974680, 2016). "Midkine has subsequently been found to be overexpressed in a number of malignant tumors." (PMID 24083030, 2013). "Midkine promoter activity was measured in cancer cell lines by the dual luciferase reporter assay." (PMID 18717994, 2008). "Serum midkine concentrations may thus be a useful marker not only for cancer screening but also for predicting prognosis of OSCC patients." (PMID 18682710, 2008). "MDK plays important roles in the nervous system, inflammation, and cancer." (PMID 18275606, 2008). "Furthermore, MDK treatment enhanced tumorigenesis in vivo and correlated with increased cancer cell proliferation in younger patients with ER-positive breast cancer, which the authors link to sterol regulatory element-binding transcription factor 1 (SREBF1) via PI3K/AKT/mTOR signaling." (PMID 40429950, 2025). "Indeed, MDK expression facilitates enhanced Treg infiltration in several cancers." (PMID 40429950, 2025). "Similarly, the hypoxic conditions often found in cancers can also promote MDK signaling." (PMID 40429950, 2025). "Therefore, Ugonin P inhibits MDK production in cancer cells by upregulating miR-223-3p synthesis." (PMID 40520001, 2025). "Furthermore, the inhibition or downregulation of MDK using RNA interference (RNAi) or siRNA has been shown to enhance the effectiveness of chemotherapeutic agents by restoring drug sensitivity in resistant cancer cells." (PMID 40500394, 2025). "However, the MES cancer cell lowly expressed MDK gene, which interacts with Tfh cells by ITGB1." (PMID 39649843, 2025). "As such, small molecule inhibitors targeting MDK may have utility in treating women’s cancers." (PMID 40429950, 2025). "Collectively, the MDK gene may influence cancer progression through its interaction with c‐Myc." (PMID 40468625, 2025). "Additionally, Midkine is another emerging mitogenic growth factor expressed in both cancer and atherosclerotic lesions across all disease stages that may be particularly relevant in older patients." (PMID 41007845, 2025). "MDK, a pro-tumor growth factor, is highly expressed in various types of cancer and has been shown to promote cell proliferation, migration, and survival.In LUAD, MDK expression correlates with poor prognosis, yet its potential role in modulating immune suppression remains unclear." (PMID 40396179, 2025). "Finally, several studies in various cancers highlight MDK as an emerging player in drug resistance." (PMID 38247828, 2024). "While MDK negatively contributes to cancer progression and metastasis formation via its anti-apoptotic and growth-promoting effects in the peripheral compartment as well as in the CNS, these functions may also have beneficial roles in the context of injuries and tissue regeneration." (PMID 38098484, 2023). "Based on these findings, we propose that MDK may be used as a potential therapeutic target to eliminate IFN-γ-elicited pro-metastatic adverse effect, and that combined MDK utilization may expand the application of IFN-γ in cancer and improve the clinical benefits from IFN-γ-based therapies." (PMID 35747815, 2022). "In summary, targeting the high expression of MDK may provide therapeutic benefits in human cancers." (PMID 35487917, 2022). "In addition, MDK levels have been shown to be increased in different cancers 14-18." (PMID 32308772, 2020). "In addition, hypoxia-induced MDK affects cancer cells through an autocrine mechanism." (PMID 32847073, 2020). "Thus, targeting MDK has been considered to be a promising strategy for cancer therapy." (PMID 29872508, 2018).